NFATC3 (nuclear factor of activated T cells 3)
Diseases named in the same sentence as NFATC3 in open-access papers (continued):
Sharing a sentence is not in itself a finding about the gene and the disease.
colon cancer (8 papers, 2011 to 2023). "In glioblastoma and colon cancer cells, hypoxia induces the expression of the calcium channel protein, thus activating Ca2+ entry and NFATc3 to enhance tumor cell proliferation and invasiveness." (PMID 35484132, 2022). "In our previous research by chromatin IP (CHIP), we confirmed that NFATc3 indeed bond to the c-Myc promoter in colon cancer to yield increased levels of c-Myc." (PMID 28881766, 2017). "For example, NFATc1 promotes proliferation of hepatocellular carcinoma cells, NFATc2 increases the invasiveness of breast cancer cells, and NFATc3 and NFATc4 promote the progression of colon cancer." (PMID 28881766, 2017). "Same results were obtained in colon cancer cells by the same group of researchers, where potentiation of SOCE mediated by hypoxia-induced upregulation of ORAI1 determined the activation of NFATc3, enhancing hypoxia-induced invasion and angiogenesis in colon cancer cells." (PMID 35806388, 2022). "Recent studies have further indicated that hypoxia can induce the activation of NFATc3 in colon cancer cells via upregulation of Orai1, which leads to increased intracellular Ca2+ and NFATc3 nuclear anchorage, resulting in the transcriptional activation of downstream genes." (PMID 35484132, 2022). "Furthermore, we reported that ANGPTL2 activates NFATc3 in colon cancer cells." (PMID 37452654, 2023). "It was recently reported that hypoxia could trigger the activation of NFATc3 via upregulation of Orai1, which leads to increased intracellular Ca2+ and the following activation of calcineurin, resulting in NFATc3 dephosphorylation and nuclear import in colon cancer cells." (PMID 35484132, 2022). "It was recently reported that hypoxia could trigger the activation of NFATc3 in colon cancer cells." (PMID 35484132, 2022). "NFATc2 likely opposes the action of NFATc1, NFATc3, and NFATc4 in colon cancer cells as those tumors lacking NFATc2 expression most likely had a more aggressive clinical course driven in part by the unopposed actions of NFATc1, NFATc3, and NFATc4." (PMID 26795951, 2016). "NFATc3 was over-expressed in GC tissue compared with adjacent non-tumor tissue, consistent with our previous study of colon cancer patient samples, indicating that NFATc3 may act as a pro-tumorigenesis factor." (PMID 28881766, 2017).
colorectal cancer (8 papers, 2017 to 2025). A primary or metastatic malignant neoplasm that affects the colon or rectum. "In ulcerative colitis-associated colorectal cancer, NFATc3 regulates macrophage inflammation and carcinogenesis, mediated by Pou3f1." (PMID 39822413, 2024). "Pou3f1 facilitates NFATc3 in ulcerative colitis-associated colorectal cancer development." (PMID 39822413, 2024). "Furthermore, NFATc3 has been shown to enhance the proliferation and invasive capabilities of colorectal cancer (CRC) cell lines." (PMID 41562084, 2025). "A previous study showed that the anti-tumorigenic strain Faecalibaculum rodentium contributed to reduced tumor growth in colorectal cancer models, and its metabolic product, SCFAs, controlled protein acetylation and tumor cell proliferation by inhibiting calcineurin/NFATc3 activation." (PMID 40573134, 2025). "NFATC3/PLA2G15 also promotes the invasion and proliferation of colorectal cancer." (PMID 39822413, 2024).
diabetes (6 papers, 2014 to 2021). "Thus, NFATc3 may be associated with diabetic vascular dysfunction." (PMID 33791348, 2021). "In a human study of patients with valve heart diseases and diabetes, calcineurin–NFATc3 signaling was shown to correlate with the presence of atrial fibrillation." (PMID 31226824, 2019). "Diabetes-induced hyperglycemia activates NFAT, especially NFATc3, in vascular smooth muscle cells, leading to increased intravascular expression of osteopontin (OPN)." (PMID 33791348, 2021). "Diabetes increased OPN expression in the aorta of normolipidemic mice and this was prevented by pharmacological inhibition of NFAT with the NFAT-blocker A285222 or by lack of NFATc3 protein in NFATc3 deficient mice." (PMID 23755169, 2014).
Hyperglycemia (6 papers, 2014 to 2023). An increased concentration of glucose in the blood. "Acute hyperglycemia induced by an IP-GTT (intraperitoneal glucose tolerance test) resulted in increased NFATc3 nuclear accumulation and NFAT-dependent transcriptional activity in retinal vessels of NFAT-luciferase reporter mice." (PMID 25918731, 2015). "We have recently shown that hyperglycemia induces the proinflammatory cytokine OPN in mouse aorta by direct binding of NFATc3 to the OPN promoter." (PMID 25918731, 2015). "To determine the potential mechanisms by which hyperglycemia promotes myocardial fibrosis, we conducted the expression of CaN/NFATc3 pathway and a potential downstream protein of this signaling, EZH2, in the diabetic heart tissues and NRCFs exposed to high glucose for 72 h." (PMID 37735624, 2023). "The same protein–protein interactions may also contribute to activate the phosphatase calcineurin and the transcription factor NFATc3 upon chronic hyperglycemia and diabetes." (PMID 33082339, 2020). "We have previously shown that hyperglycemia effectively activates NFATc3 in the arterial wall and once activated, NFATc3 induces the expression of the pro-inflammatory matrix protein osteopontin (OPN), a cytokine that promotes atherosclerosis and diabetic vascular disease." (PMID 23755169, 2014). "A previous study showed that NFATc3 might contribute to arterial remodeling associated with hypoxia-intermittent hypoxia, and NFAT was a novel mechanism causing endothelial dysfunction under hyperglycaemia." (PMID 29641598, 2018).
atherosclerosis (5 papers, 2014 to 2025). A disease characterized by the build-up of fatty material and calcium deposition in the arterial wall resulting in partial or complete occlusion of the arterial lumen. "The NFATc3/miR-204 axis may be another target in the development of individual therapy against atherosclerosis." (PMID 37686238, 2023). "A total of 6 genes were enriched in the lipid and atherosclerosis signaling pathway (CAMK2B, VAV3, PLCB3, NFATC3, TNFRSF10B, and BCL2L1), and these genes were regulated by tRF-60:76-Val-AAC-1-M5." (PMID 36247465, 2022).
glioblastoma (5 papers, 2019 to 2025). The most malignant astrocytic tumor (WHO grade IV). "NFATc3 was the predominant factor detected in U251 cells and a collection of primary human glioblastoma cell lines, which corroborates our results." (PMID 34443374, 2021). "Our results are consistent with data generated by the TCGA Research Network showing that NFATc1 and NFATc3 are expressed in higher amount in human glioblastoma samples when compared to normal brain tissue." (PMID 31249342, 2019).
lung fibrosis (5 papers, 2010 to 2024). "Adoptive transfer of NFATc3+/+ macrophages to NFATc3+/- mice restored susceptibility to BLM-induced pulmonary fibrosis." (PMID 37523510, 2023). "A key finding was that NFATc3 deficiency significantly attenuated BLM-induced pulmonary fibrosis and inflammation, and the adoptive transfer of NFATc3+/+ macrophages into NFATc3+/- mice restored cellular and pulmonary fibrotic markers in mouse models of BLM-induced pulmonary fibrosis." (PMID 37523510, 2023). "Deficiency in NFATc3 significantly reduces the levels of fibrotic markers CCL2 and CXCL2 induced by BLM, attenuating BLM-induced pulmonary fibrosis and inflammatory response." (PMID 39301028, 2024). "In conclusion, we demonstrated that upregulated NFATc3 expression is a characteristic manifestation during the course of pulmonary fibrosis." (PMID 37523510, 2023). "Taken together, these data suggest that NFATc3 expression and cytoplasmic to nuclear translocation occurs in pulmonary macrophages correlate with the progress of pulmonary fibrosis development." (PMID 37523510, 2023). "In contrast, all the fibrotic markers, Trichrome blue staining and Ashcroft score indicating fibrosis severity were significantly attenuated in NFATc3+/- mice subjected to BLM-induced pulmonary fibrosis." (PMID 37523510, 2023). "We further assessed the degree of pulmonary fibrosis using Masson’s trichrome staining and found that there was less collagen deposition (blue pigment) in the lung interstitium of NFATc3+/- compared to NFATc3+/+ mice, indicating decreased severity of fibrosis." (PMID 37523510, 2023). "Collectively, our data demonstrate, for the first time, that NFATc3 regulates pulmonary fibrosis by regulating CCL2 and CXCL2 gene expression in macrophages." (PMID 37523510, 2023). "Recipient mice adoptively transferred with NFATc3+/- or NFATc3+/+ macrophages were subjected to BLM-induced pulmonary fibrosis and analyzed." (PMID 37523510, 2023). "Mechanistic studies revealed that NFATc3 is involved in the pathogenesis of pulmonary fibrosis by promoting CCL2 and CXCL2 production in response to damaged epithelial cells, IL-33 and Th2 cytokine stimulation." (PMID 37523510, 2023). "In summary, these results demonstrate that macrophage specific NFATc3 regulates pulmonary fibrosis development in mouse models." (PMID 37523510, 2023). "In the current study, we have observed enhanced expression and activity of NFATc3 in lung tissue of pulmonary fibrosis patients, mouse BLM-induced IPF lungs and pulmonary macrophages." (PMID 37523510, 2023). "To further confirm the role of CXCL2 in NFATc3-mediated pulmonary fibrosis, we administered recombinant mouse CXCL2 (rmCXCL2), intratracheally into NFATc3+/- mice, 8 days after BLM (i.t) stimulation." (PMID 37523510, 2023). "Our data support targeting NFATc3 as a novel strategy for prevention and treatment of pulmonary fibrosis in clinical settings." (PMID 37523510, 2023). "In the present study, we demonstrated that IPF patients and mice with the onset of BLM-induced pulmonary fibrosis show increased expression of NFATc3 in lung tissue and macrophages." (PMID 37523510, 2023). "Based on these observations, we sought to determine the molecular mechanisms by which macrophage NFATc3 regulates pulmonary fibrosis using mouse BLM-induced IPF models." (PMID 37523510, 2023). "In contrast, all the fibrotic markers, Trichrome blue staining, and Ashcroft score in NFATc3+/- mice subjected to BLM-induced pulmonary fibrosis were significantly attenuated." (PMID 37523510, 2023). "NFATc3+/+ mice subjected to BLM-induced pulmonary fibrosis showed increased accumulation of fibroblast foci, extracellular matrix protein deposition, fibrotic markers and CCL2 and CXCL2 production." (PMID 37523510, 2023). "Therefore, we sought to determine the role of NFATc3 in modulating macrophage function in BLM-induced pulmonary fibrosis." (PMID 37523510, 2023).
lung fibrosis (continued). "Having confirmed the involvement of NFATc3 in lung fibrosis and inflammation, we then determined whether the effect of NFATc3 on the progression of pulmonary fibrosis is mediated through macrophages." (PMID 37523510, 2023). "Interestingly, NFATc3+/+ mice subjected to BLM-induced pulmonary fibrosis showed increased accumulation of fibrotic foci, extracellular matrix protein deposition, fibronectin, α-SMA, CCL2 and CXCL2 production." (PMID 37523510, 2023). "In contrast, the degree of pulmonary fibrosis is significantly lower in NFATc3+/- mice." (PMID 37523510, 2023). "NFATc3+/- mice that received NFATC3+/+ pulmonary macrophages by adoptive transfer or rmCXCL2 alone showed increased pulmonary fibrosis severity and fibrotic gene expression similar to that of WT/ NFATc3+/+ mice, suggesting a pivotal role for NFATc3 in the development of lung fibrosis." (PMID 37523510, 2023). "Taken together, these data support a critical role for NFATc3 in regulating the production of CCL2 and CXCL2 in macrophages during the BLM-induced pulmonary fibrosis progression in mouse models." (PMID 37523510, 2023). "In the current study, we demonstrate that expression of NFATc3 is elevated in lung tissues and pulmonary macrophages in mice subjected to bleomycin (BLM)-induced pulmonary fibrosis and IPF patients." (PMID 37523510, 2023). "Then, we assessed whether NFATc3 regulates the production of CCL2 and CXCL2 in mouse in vivo pulmonary fibrosis models." (PMID 37523510, 2023). "Moreover, IL-33 treatment increases CCL2 and CXCL2 production in NFATc3+/+ macrophages, but not in NFATc3+/- mice, suggesting that NFATc3 regulates pulmonary fibrosis by regulating CCL2 and CXCL2 expression in macrophages." (PMID 39850880, 2024).
gastric cancer (4 papers, 2017 to 2021). A primary or metastatic malignant neoplasm involving the stomach. "The increased level of γ-H2AX was time-dependent indicating that NFATc3 knockdown did in fact cause DSB in gastric cancer cells." (PMID 31822296, 2019). "By inducing cell cycle arrest in the pre-DNA synthesis phase, we hypothesized that NFATc3 silencing may cause significant DNA damage in the gastric cancer cells." (PMID 31822296, 2019). "Our in vivo experiments further confirmed that arsenic sulfide exerted cytotoxic activity against gastric cancer cells through inhibiting NFATc3 to activate RAG1 pathway." (PMID 31822296, 2019). "These clinical data support the conclusions that NFATc3 in gastric cancer is over-expressed and that NFATc3 upregulation and RAG1 downregulation are significantly associated with poor prognosis." (PMID 31822296, 2019). "More importantly, arsenic sulfide induces DNA damage leading to cell death by inhibiting NFATc3 in gastric cancer cells." (PMID 31822296, 2019). "Mechanistically, arsenic sulfide treatment of gastric cancer cells as well as knockdown of NFATc3 induce double strand DNA break and RAG1 expression." (PMID 31822296, 2019). "Previously, we found that NFATc3 expression was obviously higher in gastric cancer tissues compared with adjacent normal tissues." (PMID 31822296, 2019). "The results showed that NFATc3 expression was significantly increased in the gastric cancer tissues while RAG1 expression was significantly decreased in the gastric cancer tissues." (PMID 31822296, 2019). "NFATc3 silencing abolished the transcriptional suppression of RAG1 leading to increased DNA DSBs in gastric cancer cells." (PMID 31822296, 2019). "Taken together, these data suggest that NFATc3 is required for the growth and survival of gastric cancer cells." (PMID 31822296, 2019). "NFATc3 was highly expressed in gastric cancer tissues and promoted tumor progression and aggressiveness." (PMID 31040921, 2019). "Our previous study showed that the expression levels of NFATc3 correlated with the sensitivity of gastric cancer cells to arsenic sulfide-induced cytotoxicity." (PMID 31822296, 2019). "In the present study, we demonstrate that NFATc3 expression was required for the growth and survival of gastric cancer cells." (PMID 31822296, 2019). "To investigate if NFATc3 is required for the growth of gastric cancer cells, we knocked down NFATc3 in three human gastric cancer cell lines: AGS, MGC803 and MKN45." (PMID 31822296, 2019). "To investigate the mechanisms responsible for the NFATc3 dependence by the gastric cancer cells, we performed RNA-seq analysis of NFATc3-silenced AGS and MKN45 cells and found that 22 genes were differentially expressed in both cell lines." (PMID 31822296, 2019). "We show that arsenic sulfide as well as knockdown of NFATc3 resulted in increased double-strand DNA damage in gastric cancer cells by increasing the expression of RAG1, an endonuclease essential for immunoglobulin V(D) J recombination." (PMID 31822296, 2019). "We further showed that NFATc3 upregulation and RAG1 downregulation significantly associated with poor prognosis in patients with gastric cancer." (PMID 31822296, 2019). "Western blot was carried out to detect nuclear factor of activated T-cells, cytoplasmic 3 (NFATc3), cell cycle markers, DNA damage pathway protein expression as well as other protein expression in gastric cancer cell lines." (PMID 31822296, 2019). "This indicates that NFATc3 was responsible for the increased level of γ-H2AX upon arsenic sulfide treatment of gastric cancer cells and demonstrates that arsenic sulfide induces DNA damage by inhibiting the NFATc3 pathway." (PMID 31822296, 2019). "Here we show that NFATc3 expression is critically important for growth and survival of gastric cancer." (PMID 31822296, 2019).
gastric cancer (continued). "To verify that the inhibitory effect of arsenic sulfide on gastric cancer cells was meditated by NFATc3, we established an NFATc3-overexpressing cell line and treated it with different concentrations of arsenic sulfide." (PMID 31822296, 2019). "Our data also showed that, NFATc3 promoted the proliferation of gastric cancer cells by regulating c-Myc." (PMID 28881766, 2017). "This makes it an ideal targeted therapy for NFATc3-dependent gastric cancer." (PMID 31822296, 2019). "Here, we found that NFATc3 is required for the growth and survival of gastric cancer cells." (PMID 31822296, 2019). "We investigated if arsenic sulfide inhibits gastric cancer by targeting NFATc3 to increase DSB." (PMID 31822296, 2019). "Furthermore, NFATc3 expression was significantly higher in gastric cancer tissues compared with the adjacent normal tissues." (PMID 28881766, 2017). "The baseline expression of NFATc3 varied distinctly in gastric cancer cell lines (AGS, MGC803, MKN28, MKN45, and SGC7901) and the sensitivity of these cells to As4S4 was dissimilar, with AGS and MGC803 cells showing higher sensitivity while the SGC7901 cells relatively resistant." (PMID 28881766, 2017). "In other words, gastric cancer cells may be addicted to NFATc3." (PMID 31822296, 2019). "Furthermore, arsenic sulfide, which enhances ROS targeting NFATc3, may be an effective drug for the treatment of gastric cancer." (PMID 31822296, 2019). "In conclusion, As4S4 inhibited the proliferation of gastric cancer cells through NFATc3/c-Myc pathway and the diverse sensitivity among different cell lines correlated with the expression level of NFATc3 indicating that NFATc3 may be a potential therapeutic target in gastric cancer." (PMID 28881766, 2017). "Thus, NFATc3 may be a potential target for gastric cancer treatment." (PMID 31822296, 2019). "We then further verified NFATc3 and RAG1 dysregulation in six pairs of gastric cancer tissues and matched adjacent nonmalignant tissues by qRT-PCR." (PMID 31822296, 2019).